IL27RA (interleukin 27 receptor subunit alpha)
Diseases named in the same sentence as IL27RA in open-access papers (continued):
Sharing a sentence is not in itself a finding about the gene and the disease.
lung carcinoma (2 papers, 2015 to 2022). "Since expression of gp130 has been documented in lung cancer, we only assessed IL-27Rα expression in both cancerous and normal lung samples (from both cancer and control patients)." (PMID 25638163, 2015). "Notably, IL-27Rα expression in microdissected bronchial epithelium from normal samples of patients with lung cancer was analogous to that in control patients." (PMID 25638163, 2015).
metastatic disease (2 papers, 2015 to 2025). "Furthermore, within AC, metastatic tumors revealed significantly (P < 0.05) higher expression levels of IL-27Rα mRNA than normal bronchial epithelia." (PMID 25638163, 2015).
psoriasis (2 papers, 2024). An autoimmune condition characterized by red, well-delineated plaques with silvery scales that are usually on the extensor surfaces and scalp. "More importantly, Il27ra deficient γδ T cells are more pathogenic in an imiquimod-induced murine psoriasis model, while intracutaneous injection of rmIL-27 ameliorates psoriatic inflammation." (PMID 38982043, 2024). "In summary, this work uncovered the metabolic basis for the immune regulatory activity of IL-27 in restraining γδ T17 mediated inflammation, which provides novel insights into IL-27/IL-27Ra signaling, γδ T17 biology and the pathogenesis of psoriasis." (PMID 38982043, 2024). "This work uncovers the metabolic basis for the immune regulatory activity of IL-27 and provides novel insights into IL-27/IL-27Ra signaling, γδ T17 biology and the pathogenesis of psoriasis." (PMID 38982043, 2024). "Moreover, precautionary or therapeutic intracutaneous injection of IL-27 proteins significantly ameliorated the pathogenesis of psoriasis with dramatic inhibition of γδ T17 cells even though psoriatic γδ T cells had reduced expression of IL-27Ra." (PMID 38982043, 2024).
respiratory infection (2 papers, 2017 to 2023). "Corresponding to the differences seen in infected IL-27Rα-/- mice, Th2-like responses are associated with enhanced lung damage in murine and human respiratory infection." (PMID 28129374, 2017).
retinitis (2 papers, 2021 to 2024). Inflammation of the retina. "We found that the eyes of IL-27Rα−/− mice exhibited more severe vasculitis/retinitis and perivascular exudates by day 21 at the peak of EAU, WT littermates developed focal lesions around optic nerve and less inflammatory exudates at the same time, and naïve WT mice served as the healthy control." (PMID 34299138, 2021).
Splenomegaly (2 papers, 2020 to 2024). Abnormal increased size of the spleen. "Therefore, we hypothesised that the more rapid development of splenomegaly in L. donovani-infected Il27ra-/- mice was caused by an unbalanced Th1 and Tr1 cell response." (PMID 33049000, 2020).
abdominal aortic aneurysm (1 paper, 2020). Enlargement and ballooning of the vessel that supplies arterial blood to the abdomen, pelvis and legs. "IL-27Rα deficiency could protect abdominal aortic aneurysm development through limiting accumulation of myeloid cells and Ang II-induced hematopoietic stem cell expedition." (PMID 32075272, 2020).
B-cell lymphomas (1 paper, 2020). "Finally, we found upregulation of IL27RA, which is specifically overexpressed in MALT lymphoma compared with other B-cell lymphomas." (PMID 32201227, 2020).
Bell's palsy (1 paper, 2025). Partial or complete paralysis of the facial muscles of one side of a person's face. "Checking the related studies of other proteins, we found that IL-27RA, OSM and JAK/STAT signaling pathways may play a key role in the development of Bell’s palsy." (PMID 40299566, 2025).
carotid atherosclerosis (1 paper, 2017). A thickening and loss of elasticity of the walls of carotid arteries that occur with formation of atherosclerotic plaques. "Herein we extend these reports by demonstrating increased plasma levels of IL-27 in 140 patients with carotid atherosclerosis, and increased mRNA levels of IL-27 subunits and IL-27RA, as well as increased expression of IL-1β and NLRP3 within the carotid lesion from 159 patients." (PMID 29176764, 2017).
co-infection (1 paper, 2015). "To test this, we utilized IL-27 receptor α knock-out (IL-27Rα−/−) mice and examined the impact of the IL-27 signaling on viral, bacterial and co-infection pathogenesis." (PMID 25651926, 2015). "In our current study, IL-27Rα−/− mice displayed increased lung pathology but decreased bacterial burden of S. aureus during co-infection." (PMID 25651926, 2015). "Thus, IL-27Rα−/− mice that have increased Type 17 cytokine responses compared to controls, have improved bacterial clearance during co-infection." (PMID 25651926, 2015).
dysplasia (1 paper, 2015). A usually neoplastic transformation of the cell, associated with altered architectural tissue patterns. "Immunohistochemistry also revealed IL-27Rα expression in AC and SCC precursor lesions, namely atypical adenomatous hyperplasia (AAH) and severe dysplasia, squamous metaplasia (SM), squamous cell carcinoma in situ (SCIS), respectively." (PMID 25638163, 2015).
E. coli infection (1 paper, 2023). "Since the number of IL-27Rα-dependent genes was marginal at base level and we observed phenotypic differences in neonates during infection, we further explored the transcriptional response during systemic E. coli infection." (PMID 36891292, 2023). "Further analysis indicated that genes upregulated by E. coli infection were generally downregulated post-infection in the absence of IL-27Rα with a similar observation made for genes downregulated by E. coli infection." (PMID 36891292, 2023). "Interestingly, compared to WT mice, the expression changes induced by E. coli infection were generally smaller in the KO mice, suggesting that in the absence of IL-27Rα the transcriptional program of macrophages became less responsive to E. coli infection." (PMID 36891292, 2023).
fibrosarcoma (1 paper, 2013). A malignant mesenchymal fibroblastic neoplasm affecting the soft tissue and bone. "We therefore examined the effect of IL-27 signaling on MCA-induced fibrosarcoma development by administering MCA to groups of Il27ra+/+ or Il27ra−/− mice." (PMID 23554861, 2013).
osteitis (1 paper, 2018).
osteomyelitis (1 paper, 2022). An acute or chronic inflammation of the bone and its structures due to infection with pyogenic bacteria. "Therefore, we repeated the in vivo S. aureus osteomyelitis experiments using IL-27 receptor α knockout (IL-27Rα−/−) mice." (PMID 36028492, 2022). "At the onset of S. aureus osteomyelitis, osteoblasts and macrophages induce IL-27 secretion via TLR activation, and this process is dependent on the autoregulatory IL-27/IL-27Rα signaling pathway." (PMID 36028492, 2022). "To test this hypothesis, we evaluated S. aureus osteomyelitis in WT and IL-27Rα−/− mice with and without exogenous IL-27 induction by intramuscular injection of rAAV-IL-27p28 or rAAV-GFP, respectively." (PMID 36028492, 2022).
papilloma (1 paper, 2016). A benign epithelial neoplasm that projects above the surrounding epithelial surface and consists of villous or arborescent outgrowths of fibrovascular stroma. "IL27-induced papilloma initiation was compromised in IL27RA−/− mice, suggesting that IL27 signaling through its receptor, IL27RA, is needed to promote papilloma initiation." (PMID 27738312, 2016).
peritonitis (1 paper, 2020). Inflammation of the peritoneum (tissue that lines the abdominal wall and covers most of the organs in the abdomen). "Improved infection control in adult mice lacking EBI3 or IL-27Rα occurs during both M. tuberculosis and P. aeruginosa infections or CLP-induced peritonitis." (PMID 31818960, 2020).
rectal cancer (1 paper, 2023). A primary or metastatic malignant neoplasm that affects the rectum. "IL27RA is positively correlated with the infiltration of CD8 T cells, DCs and neutrophils in rectal cancer." (PMID 37779866, 2023).
respiratory syncytial virus infection (1 paper, 2016). "IL27RA-deficient mice are prone to enhanced expression of Th17-related cytokine and exacerbation of mucus secretion in the lung following respiratory syncytial virus infection." (PMID 27661616, 2016).
sarcoma (1 paper, 2013). A usually aggressive malignant neoplasm of the soft tissue or bone. "At a higher MCA dosage of 25 μg per mouse, 84% (n = 19) of Il27ra−/− mice developed sarcoma compared to 68% (n = 19) from Il27ra+/+ mice." (PMID 23554861, 2013).
schizophrenia (1 paper, 2025). A major psychotic disorder characterized by abnormalities in the perception or expression of reality. "Interleukin-27 Receptor Subunit Alpha (IL-27Rα) is the only significant shared element among ADHD, schizophrenia, and T1D." (PMID 40082977, 2025).
ZIKV infection (1 paper, 2025). "However, there was a significantly greater incidence of resorption in the fetuses of IL-27-neutralized (28% total resorption; 8% early resorption) and IL27RA−/− (23.1% total resorption; 5.1% early resorption) dams during congenital ZIKV infection." (PMID 40502752, 2025).
infection (47 papers, 2011 to 2025). The state of being infected such as from the introduction of a foreign agent such as serum, vaccine, antigenic substance or organism. "After infection, Il27ra–/– LTHSCs remained deficient in the mixed chimeras, but MPs from both lineages were equivalent (right bars)." (PMID 41396163, 2025). "There were 634 genes that were differentially expressed between WT and KO neonates during infection; 271 were significantly upregulated and 363 were downregulated with IL-27Rα deficiency." (PMID 36891292, 2023). "Of note, neonatal pups deficient in IL-27Rα exhibited decreased mortality, improved weight gain, reduced inflammation, and enhanced control of bacterial growth during infection when compared to their WT counterparts." (PMID 36891292, 2023). "Lower levels of inflammatory cytokines in IL-27Rα-deficient neonates during infection are consistent with reduced bacterial burdens." (PMID 31818960, 2020). "In multiple models of infection the loss of the IL-27Rα has been associated with CD4+ T cell-mediated immunopathology linked with the overproduction of IFN-γ." (PMID 28129374, 2017). "Depletion of CD4+ T cells in IL-27Rα-/- mice led to a decrease in AAMs and reduced weight loss after infection, while eliminating STAT6 signaling in IL-27-deficient mice reduced Th2 responses and decreased mortality." (PMID 28129374, 2017). "Accordingly, mice deficient in IL-27Rα − /− infected with intracellular pathogens including Listeria, Leishmania, and Mycobacteria are more susceptible to the infections." (PMID 25126585, 2014). "For instance, mice deficient in IL-27Rα exhibit reduced Th1 responses following infection with intracellular pathogens such as Listeria monocytogenes and Leishmania major." (PMID 24068935, 2013). "However, other studies suggest this deficiency is only apparent early during infection, as IFNγ responses later in infection are equal or even greater in IL-27Rα KO mice." (PMID 38390338, 2024). "Moreover, a role for Th17 cells cannot be excluded, however we were not able to detect IL-17 production by CD4+ T cells in the context of Il27ra-deficiency in this infection model." (PMID 33049000, 2020). "Although it is still unclear whether IL-27 also regulates IL-10 expression by T cells during M. tuberculosis infection, IL-27Rα signaling in CD4+ T cells has been recently shown to confer susceptibility to this infection." (PMID 28584007, 2017). "To explore whether IL-27 signalling was associated with changes in CD4+ T cell metabolism during infection, we first measured mitochondrial mass and membrane potential using MitoTracker dyes in WT and Il27ra-/- CD4+ T cells and Th1 cells 14 days after L. donovani infection." (PMID 33049000, 2020). "Conversely, IL-27Rα KO neonates increase CXCR2 expression significantly in the spleen during infection but fail to upregulate CXCL2 transcripts." (PMID 40977737, 2025). "Here we further explored the mechanistic insights of the CXCR2/CXCL2 signaling axis limiting the infection in WT and IL-27Rα KO neonatal mice using an n vivo model and ex vivo studies with primary cells." (PMID 40977737, 2025). "In a S. aureus pneumonia murine model, IL27Rα-/- mice decreased neutrophil and macrophage recruitment to the infection site compared to the WT mice." (PMID 34079555, 2021). "In the late phase of infection, however, IL-27Rα-/- mice also suffer from uncontrolled chronic hyper-inflammatory immune responses accompanied by excessive systemic production of pro-inflammatory cytokines." (PMID 35116036, 2021). "In a murine tuberculosis model, IL-27Rα-/- mice showed improved control of bacterial growth and decreased bacterial burden in lung and spleen on days 30 through 125 following infection." (PMID 34079555, 2021). "TNF-α levels were lower in Ly6B.2+ cells from IL-27Rα−/− pups during in vitro infection and marginally higher in BMDMs at 6 h only." (PMID 31818960, 2020).
infection (continued). "Ly6B.2+ cells and bone marrow-derived macrophages (BMDMs) from IL-27Rα−/− mice eliminated E. coli with increased efficiency early during infection." (PMID 31818960, 2020). "It was reported that IL-27RA−/− mice have an exaggerated lung immunopathology after the infection with IFV, that correlated with increased levels of CD4+ and CD8+ T cells producing IL-17 and a strong neutrophil infiltration." (PMID 33133080, 2020). "In comparison to chronic LCMV infection, during acute LCMV infection, circulating DbNP396–404+ CD8+ T cell numbers were similar in WT and Il27ra−/− mice throughout infection; however, DbGP33–41+ numbers were elevated in the absence of WSX-1." (PMID 29593047, 2018). "The numbers of NK cells in the spleen both prior to and 24 h after infection were unaffected by the deletion of Il27ra." (PMID 29593047, 2018). "Following infection with the parasite Trichuris muris, IL-27Rα KO mice exhibit accelerated expulsion of larval parasites associated with elevated production of parasite-specific IL-4, IL-5, and IL-13." (PMID 25633106, 2015). "Following Toxoplasma gondii infection in IL-27Rα − /− mice, a robust IFNγ response is induced and the clearance of the infection is rapidly achieved." (PMID 25126585, 2014). "IL-27 plays a role in the development of IFNγ+IL-10+ CD4+ T cells during experimental L. major and Listeria monocytogenes infection in vivo, as assessed using IL-27Rα−/− mice." (PMID 22911108, 2012). "Additionally, both the IL-6Rα and GM-CSFRα showed enhanced expression during infection, further differing from IL-27Rα." (PMID 39868131, 2025). "That expression of these genes was lower in IL-27Rα-infected pups may suggest a link with other metabolic pathways and improved maintenance of weight observed during infection." (PMID 36891292, 2023). "IL-27Rα−/− mice exhibit reduced levels of inflammatory cytokines during infection." (PMID 31818960, 2020). "Here we show that IL-27 signalling plays a pivotal role in generating Tr1 cells during infection, whereby Il27ra-/- mice had improved parasite control but accelerated splenic pathology, associated with an increased proportion of Th1 cells, relative to Tr1 cells." (PMID 33049000, 2020). "We found no impact of Il27ra-deficiency on the establishment of infection or growth of parasites in host macrophages." (PMID 33049000, 2020). "Basically, IL-27Rα expression may be up-regulated in inflammation processes, such as infection and other inflammatory diseases." (PMID 32075272, 2020). "Interestingly, however, the functionality of NK cells 24 h after LCMV Cl13 infection was altered, with Il27ra-−/− NK cells showing reduced granzyme B and increased IFN-γ production compared to WT NK cells." (PMID 29593047, 2018). "The numbers of CD8+ DCs, CD11b+ DCs, and CD11c− CD11b+ myeloid cells in the spleen 24 h after infection were unaffected by Il27ra deletion; however, the number of pDCs at this time was significantly reduced, by approximately 2-fold, in Il27ra−/− mice compared to WT mice." (PMID 29593047, 2018). "As blockade of IL-4 prior to infection with Lesihmania major induces normal parasite specific Th1 responses in IL-27Rα KO mice, the susceptibility in these mice is not due to a defect in Th1 immunity, but rather a consequence of accelerated Th2 responses." (PMID 25633106, 2015). "However, IL-27 does not seem to play a direct role in exacerbation of S. aureus by influenza virus, as WT and IL-27Rα−/− mice had similar fold exacerbation of S. aureus secondary infection." (PMID 25651926, 2015). "However, since high numbers of neutrophils are known to be associated with susceptibility in the chronic phase of TB, the enhanced levels of neutrophils in the lungs of IL-27Rα-/- mice may contribute to the emerging immunopathology during late infection." (PMID 35116036, 2021).